TRAJ26 (T cell receptor alpha joining 26)
Gene: T-cell receptor joining (J) gene on chromosome 14 (22,518,446 to 22,518,505, forward strand). Ensembl gene ENSG00000211863.
Diseases named in the same sentence as TRAJ26 in open-access papers:
TRAJ26 is named in the same sentence as 1 disease in open-access papers, as found by Europe PMC text mining. Sharing a sentence is not in itself a finding about the gene and the disease. The quoted sentences say what the papers report.
cancer (1 paper, 2025). A tumor composed of atypical neoplastic, often pleomorphic cells that invade other tissues. "Of the remaining cancer-activated MR1-restricted TCRs, some used the MAIT cell–preferred TRAJ20 and TRAJ12 to generate a similarly placed tyrosine and others used TRAJ26, TRAJ47, or TRAJ32 to encode this tyrosine residue." (PMID 39744940, 2025).